DOCK8 (dedicator of cytokinesis 8)
Diseases named in the same sentence as DOCK8 in open-access papers (continued):
Sharing a sentence is not in itself a finding about the gene and the disease.
Wiskott-Aldrich syndrome (19 papers, 2016 to 2025). Wiskott-Aldrich syndrome (WAS) is a primary immunodeficiency disease characterized by microthrombocytopenia, eczema, infections and an increased risk for autoimmune manifestations and malignancies. "Lymphomas with similar a phenotype have been identified in other inborn errors of immunity including Wiskott Aldrich Syndrome and X-linked lymphoproliferative disease 1 and DOCK8 deficiency." (PMID 38758417, 2024). "For instance, it has a positive clinical impact on ADA deficiency, Wiskott-Aldrich syndrome (WAS), Fanconi anemia, and in variants affecting DOCK8, ITGB2, or CXCR4." (PMID 40711587, 2025). "SCID, CIDs, DiGeorge syndrome, Wiskott-Aldrich syndrome, Ataxia telangiectasia, Dyskeratosis congenita, ORAI-1 deficiency, CGD, X-linked Agammaglobulinemia, ALPS, STAT1 gain of function, CTLA-4 deficiency, GATA-2 deficiency, TRAPS, FMF, NEMO, TIM3, DOCK8, STAT2, STAT3, PIK3CD." (PMID 41049857, 2025). "Cytoskeletal disorders include Wiskott-Aldrich syndrome (WAS), Wiskott-Aldrich syndrome protein (WASP) WAP interacting protein (WIP), Dedicator of cytokinesis 8 (DOCK8) deficiency and Serine/threonine kinase 4 (STK4) deficiency." (PMID 37755421, 2023). "The current set of targeted PIDDs includes ADA deficiency (ADA), Dedicator of cytokinesis 8 (DOCK8) deficiency, X-Linked Chronic Granulomatous disease (XL-CGD), Wiskott-Aldrich Syndrome (WAS), and X-Linked Agammaglobulinemia (XLA)." (PMID 32296420, 2020).
allergies (17 papers, 2016 to 2025). "Patients with HIES caused by DOCK8 deficiency are more susceptible to developing allergic diseases (e.g., asthma, food allergies, and atopic dermatitis) than those with HIES caused by STAT3 mutations." (PMID 34867940, 2021). "Overall, the results provide new insight into the potential design of Breg-based or IL-21-based therapeutic strategies for allergic diseases, including asthma associated with DOCK8 deficiency." (PMID 34867940, 2021). "Although the diagnosis of DOCK8 deficiency, based on the characteristic phenotype, seems straightforward, the presence of mild and atypical phenotypes overlaps with other PIDs and allergic diseases." (PMID 35386989, 2021). "Data from this study provide new insight into the potential design of Breg-based or IL-21-based therapeutic strategies for allergic diseases, including asthma in those with DOCK8 deficiency." (PMID 34867940, 2021). "Patients with susceptibility to infection but less severe allergic disease were identified to carry a functional wild-type DOCK8 allele in lymphocyte subpopulations due to somatic reversion of the mutated DOCK8 alleles." (PMID 26680607, 2016). "Recently identified functions of DOCK8 explain why its loss might result in allergy; for example, generation of IgE-promoting IL-13+ follicular helper T cells." (PMID 34867940, 2021). "In line with this, patients with large deletions in the DOCK8 gene experience increased susceptibility to pathogenic infections yet also exhibit allergic diseases, leading to great interest surrounding DOCK8 in the field of immunology, which has recently been reviewed in great detail." (PMID 33684443, 2021). "Further studies should clarify whether Breg cells are involved in the onset of allergic disease under conditions of DOCK8 deficiency." (PMID 34867940, 2021). "Furthermore, DOCK8 deficiency in humans is associated with clinical allergy to foods, implicating this as a key susceptibility gene to food-induced anaphylaxis." (PMID 29370173, 2018). "However, the role of DOCK8-deficient B cells in the pathogenesis of allergic diseases remains unclear." (PMID 34867940, 2021). "For instance, allergy is known to be frequent in people with a CARD11 (AD DN) deficiency, a DOCK8 deficiency or a PGM3 deficiency." (PMID 41142799, 2025). "Outcome was assessed by laboratory tests, lymphocyte subsets, intracellular DOCK8 protein flow cytometry, T-cell proliferation analysis, and multiparameter immunoblot allergy screening." (PMID 34080085, 2021). "His clinical phenotype had some overlap with STAT3 deficiency, and did not present with hallmarks of DOCK8 deficiency including allergic diseases and cutaneous viral infections." (PMID 36703986, 2022). "DOCK8 deficiency is a HIES; therefore, it is associated with a high incidence of allergic disease." (PMID 34867940, 2021). "We propose that the absence of Bregs under conditions of DOCK8 deficiency contributes to allergy and chronic inflammation in these patients." (PMID 34867940, 2021). "DOCK8-deficient B cells show diminished responses to TLR9 signaling, suggesting a possible defect in IL-10-producing Breg cells in those with DOCK8 deficiency, which may contribute to allergies." (PMID 34867940, 2021). "The highest prevalence of allergy was found in patients suffering from genetic disorders caused by variants in DOCK8, CARD11 (AD DN), ARPC1B, and PLCG2, while there were no occurrences of allergy in patients with defects in the LRBA and RAG1 genes." (PMID 41142799, 2025). "In humans, loss-of-function mutations in dedicator of cytokinesis 8 (DOCK8) result in a rare, autosomal recessive primary immunodeficiency, with recurrent infections, higher prevalence of allergies and cancers, elevated IgE, and a lack of long-term immune memory." (PMID 39121196, 2024).
atopic dermatitis (16 papers, 2017 to 2025). "Severe Th2-driven atopic dermatitis and asthma are common in several IEIs, including DOCK8 deficiency, STAT3 loss-of-function, and Wiskott–Aldrich syndrome, often refractory to conventional therapies." (PMID 41357247, 2025). "The clinical phenotype of dedicator of cytokinesis 8 (DOCK8) deficiency, characterized by allergic manifestations, increased infections, and increased IgE levels, overlaps with the clinical presentation of atopic dermatitis (AD)." (PMID 35386989, 2021). "DOCK8-deficient patients develop atopic dermatitis, asthma, and severe allergies to food and environmental antigens in early infancy." (PMID 31718082, 2019). "Atopic dermatitis and DOCK8 deficiencies share similar clinical symptoms including eczema, eosinophilia, and characteristic elevated levels of serum Immunoglobulin E (IgE)." (PMID 31718082, 2019). "Here we show that CD4+ T cells from DOCK8-deficient mice produce large amounts of IL-31, a major pruritogen associated with atopic dermatitis." (PMID 28067314, 2017). "In addition, patients with DOCK8 deficiency characteristically manifest with dermatitis-like skin lesions resembling atopic dermatitis (AD)." (PMID 35386989, 2021). "DOCK8-deficiency can cause atopic dermatitis but the mechanism is unclear." (PMID 28067314, 2017). "The Severity Scoring of Atopic Dermatitis (SCORAD) and the Visual Analogue Scale (VAS) pruritus scores were calculated for both DOCK8-deficient and AD groups (table was reproduced with permission)." (PMID 31718082, 2019). "The clinical picture of atopic dermatitis (AD) overlaps with DOCK8 deficiency, but, unlike the latter, patients with AD are mostly susceptible to superficial infections with Staphylococcus aureus, and deep-seated infections rarely occur." (PMID 35386989, 2021). "However, our previous studies showed similar N-glycan profiling and in vivo stability of IgE proteins among samples derived from patients with elevated IgE-associated atopic dermatitis, HIES with LOF-STAT3, PGM3 insufficiency, and DOCK8 deficiency, compared to healthy individuals (unpublished data)." (PMID 39776909, 2024). "In our case, the patient had a history of atopic dermatitis without any severe infections until 16 months of age, when he presented with SLE as the first symptom of DOCK8 deficiency." (PMID 33787566, 2021).
Autosomal recessive hyper-IgE syndrome (15 papers, 2012 to 2025). Autosomal recessive hyper IgE syndrome (AR-HIES) is a very rare severe primary immunodeficiency disorder characterized by the clinical triad of highly elevated serum IgE levels, recurring staphylococcal skin abscesses, and recurrent pneumonia. "Most of the rare variation was found in DOCK8 (21 missense variants at 13 loci in 19 patients), biallelic LoF variants of which cause autosomal recessive hyper-IgE syndrome." (PMID 37533579, 2023). "Some cases of autosomal recessive hyper IgE syndrome will have a homozygous mutation of the cytokinesis gene, dedicator of cytokinesis 8 (DOCK8) that leads to a disruptive production of a protein involved in the regulation of actin skeleton." (PMID 25379309, 2014). "Loss of dedicator of cytokinesis 8 (DOCK8) protein function leads to the most common form of autosomal recessive HIES (AR-HIES)." (PMID 23283142, 2012). "Additionally, autosomal recessive hyper IgE syndrome (AR-HIES) patients have DOCK8 mutations that block STAT3 signalling and impair T helper 17 cell differentiation." (PMID 32915198, 2020). "An early analysis of patients with autosomal recessive hyper IgE syndrome (AR-HIES) showed that these patients had defects in Th17 differentiation, and some of them were DOCK8 deficiency." (PMID 36386145, 2022). "Recent literature has also described an autosomal recessive hyper-IgE syndrome (AR-HIES), caused by a deficiency in DOCK8, resulting in a variety of symptoms and diseases including atopy, autoimmunity risk, malignancies, recurrent viral/bacterial infections, and CMC." (PMID 30510552, 2018).
eosinophilia (15 papers, 2012 to 2025). "Eosinophilia was seen in all the patients, albeit the counts were higher in the DOCK8-deficient cohort than AD; high counts in DOCK8 deficiency cannot be used as the only criterion for diagnosis eosinophils can be elevated in many other diseases." (PMID 35386989, 2021). "While eosinophilia was present in all patients, the counts were significantly different in the DOCK8-deficient cohort compared with AD." (PMID 31718082, 2019). "A TH1-deficient phenotype and cytokine abnormalities with TH2 activation may explain eosinophilia and IgE overproduction in DOCK8 deficiency." (PMID 34080085, 2021). "Until recently DOCK8 deficiency was termed DOCK8-related Hyper Immunoglobulin E (IgE) Syndrome (HIES), as it is characterized by elevated IgE levels, eosinophilia, and recurrent infections." (PMID 35373187, 2022). "DOCK8 deficiency accounts for the majority of AR-HIES and is characterized by extensive cutaneous viral infections (herpes simplex, varicella zoster, human papillomavirus, and molluscum contagiosum), central nervous system (CNS) complications, elevated IgE, and eosinophilia." (PMID 27222657, 2016).
Intellectual disability (12 papers, 2012 to 2024). "The first was a loss at 9p24.3 involving the gene DOCK8 and has been previously linked with intellectual disability." (PMID 26379700, 2015). "The 9p24.3 duplication segment contains genes like DOCK8 and may be associated with autism spectrum disorders, intellectual disabilities/developmental delay, and other conditions." (PMID 38580914, 2024). "DOCK8 is linked to altered neurodevelopment and intellectual disability." (PMID 35501310, 2022). "In addition, evidence was recently presented supporting a causal relationship between heterozygous disruption of DOCK8 and mental retardation, pervasive developmental disorders, autism, and bipolar disorders." (PMID 30647996, 2019). "The 9p24.3 locus, which contains the DOCK8 gene overlaps with linkage regions identified in large autism extended pedigrees, and disruption of DOCK8 has previously been implicated in two cases of intellectual disability and developmental delay." (PMID 23825557, 2013). "Heterozygous changes in the DOCK8 gene have been previously reported in two unrelated patients, one by deletion testing and one by a translocation breakpoint; these disruptions are associated with intellectual disability and developmental disability (MRD2, MIM ID# 614113)." (PMID 23227143, 2012). "We describe three unrelated patients with autism spectrum disorders and intellectual disabilities / developmental delay who are carriers of the 9p24.3 duplication including DOCK8 and KANK1." (PMID 33455084, 2021). "In the DECIPHER dataset, 16 subjects with intellectual disability carry DOCK8 duplications/gains and ten carry KANK1 duplications/gains." (PMID 29191242, 2017). "Genetic duplications of 9p24.3, and therefore the DOCK8 and KANK1 genes, are associated with autism spectrum disorders (ASD), intellectual disability/developmental delay (ID/DD), attention deficit hyperactivity disorder (ADHD), epilepsy, learning problems, and language disorders." (PMID 33455084, 2021). "Recent studies suggest that duplication of the 9p24.3 chromosomal locus, which includes the DOCK8 and KANK1 genes, is associated with autism spectrum disorders (ASD), intellectual disability/developmental delay (ID/DD), learning problems, language disorders, hyperactivity, and epilepsy." (PMID 33455084, 2021). "DOCK8 is expressed in adult and fetal brain tissues and deletion or translocation breakpoints that disrupt its function have been found in individual patients with intellectual disability." (PMID 29191242, 2017). "AFF2, DOCK8, NIPBL, and RPS6KA3 were implicated in intellectual disability." (PMID 23227143, 2012). "According to the literature, CER1 and FREM1 have been suggested as responsible for trigonocephaly, DOCK8 has been proposed as a candidate gene for mental retardation and seizures, FOXD4 has been related to speech and language delay, and DMRT1 may play a role in sex reversal." (PMID 36672887, 2023).
food allergies (9 papers, 2018 to 2025). "Hyper-IgE states (e.g., in DOCK8 or CARD11 deficiency) are also recognized to accentuate food allergy as a clinical manifestation." (PMID 41142799, 2025). "Food allergy was reported in 5.6% of patients overall, with the highest prevalence in those with DOCK8 deficiency." (PMID 41142799, 2025). "Compared to other PIDs (even those with significantly elevated IgE levels, such as DN mutations in STAT3), DOCK8 deficiency leads to an extremely high frequency of severe food allergies which is a distinctive aspect of DOCK8 deficiency." (PMID 40040707, 2025). "Persistent food allergies post-HSCT are commonly seen in DOCK8-deficient patients without correlation with chimerism and are slow to improve post-HSCT, presumably due to persistence of long-lived IgE-producing plasma cells and tissue-resident memory B-cells." (PMID 34080085, 2021). "Her recurrent viral infections, high eosinophil counts, multiple food allergies, and failure to thrive raised suspicion of DOCK8-HIES3–5,11, while the lack of lymphopenia, rather normal to high lymphocyte counts, and particularly the DOCK8 protein expression in PBMCs argued against DOCK8-HIES." (PMID 30425284, 2018).
lymphopenia (9 papers, 2011 to 2025). Reduction in the number of lymphocytes. "In autosomal recessive (AR) DOCK8 deficiency, warts were reported in >40% of patients that were characterized by T and NK cell lymphopenia." (PMID 37317175, 2023). "A decrease in the heme-scavenging proteins renders patients susceptible to increased bacterial infections, as seen in patients with DOCK8 deficiency, who present with a wide spectrum of infections and lymphopenia with a T-cell senescence profile." (PMID 35386989, 2021). "Immune assessments of DOCK8 mutated AR-HIES patients reveal T cell lymphopenia with low counts of both CD4+ and CD8+ T cells, as well as impaired T cell expansion from activated peripheral blood mononuclear cells in vitro." (PMID 22085750, 2011). "Lymphopenia suggests a T‐cell production or survival defect, often seen in CID (e.g., DOCK8 deficiency, WAS, and WAS‐like syndromes)." (PMID 41177946, 2025). "Among patients with isolated CD4 lymphopenia and variable serum immunoglobulin levels, 29 patients were found to have normal HLA-DR and DOCK8 expression whereas recent thymic emigrants (CD4+CD45RA+CD31+) were markedly reduced." (PMID 35655284, 2022). "CID Patients having CD4 lymphopenia are tested for HLA-DR, DOCK8 expression and T cell maturation and recent thymic immigrants (CD4+CD45RA+CD31+)." (PMID 35655284, 2022). "Disseminated warts have also been frequently found in several autosomal recessive genetic defects that present with CD4 lymphopenia (e.g., RAG1, RHOH, MST1, CORO1A, DOCK8)." (PMID 31781092, 2019). "Thus, when patients exhibit marked CD4 lymphopenia and susceptibility to infections in the absence of a bleeding disorder, MST1 deficiency should be considered along with DOCK8 deficiency." (PMID 26801501, 2016).
autoimmune disease (7 papers, 2018 to 2024). A disorder resulting from loss of function or tissue destruction of an organ or multiple organs, arising from humoral or cellular immune responses of the individual to their own tissue constituents. "DOCK8 deficiency can be presented as autoimmune disease such as SLE." (PMID 33787566, 2021). "Therefore, DOCK8 mutation may increase susceptibility to autoimmune disease in mice through upregulation of Th17 differentiation pathway." (PMID 39329018, 2024). "Most genes were related to autoimmune diseases like ATM, NCF1, MCM4, FCN3, and DOCK8 or autoinflammatory diseases associated with the release of IFN-gamma, such as PRF1, NOD2, and MEF." (PMID 37588055, 2023). "Our finding of the enhanced enrichment of ILK in ERU cases indicates a deviant influence of DOCK8 on inter- and intracellular signaling in autoimmune disease." (PMID 30120291, 2018). "Since the functional impact of differential DOCK8 protein levels in autoimmune diseases is unknown, we further investigated potential differences in protein-protein-interaction network of DOCK8 in healthy and autoimmune phenotypes with interaction proteomics." (PMID 30120291, 2018). "Amongst those, especially the identification of DOCK8 as a novel septin 7 interaction partner was a promising finding that could help to elucidate pathomechanisms in autoimmune diseases in our opinion." (PMID 30120291, 2018). "Moreover, we gained information about the role of septin 7 and its novel interactor DOCK8 in autoimmune disease." (PMID 30120291, 2018). "Taken together, these data show that DOCK8 can regulate the levels of glycolysis and oxidative phosphorylation by stabilizing the mTOR/HIF‐1α signaling pathway, thereby inhibiting the abnormal differentiation of Th17 cell and autoimmune disease development." (PMID 39329018, 2024). "So far, the effects of DOCK8 downregulation in a spontaneous autoimmune disease are not fully understood." (PMID 30120291, 2018). "Since DOCK8 is associated with important immune functions, our finding of significantly decreased DOCK8 expression and altered DOCK8 interaction network in ERU might explain changes in immune response and shows the contribution of DOCK8 in pathomechanisms of spontaneous autoimmune diseases." (PMID 30120291, 2018).
chronic granulomatous disease (7 papers, 2019 to 2025). Chronic granulomatous disease (CGD) is a rare primary immunodeficiency, mainly affecting phagocytes, which is characterized by an increased susceptibility to severe and recurrent bacterial and fungal infections, along with the development of granulomas. "Recently, the proteomic panel was expanded to eight signature peptide biomarkers to screen for five molecularly defined IEI including adenosine deaminase (ADA) deficiency, dedicator of cytokinesis 8 (DOCK8) deficiency, X-Linked chronic granulomatous disease (XL-CGD), WAS, and XLA." (PMID 34842618, 2021).